CACNA1A (calcium voltage-gated channel subunit alpha1 A)
Diseases named in the same sentence as CACNA1A in open-access papers (continued):
Sharing a sentence is not in itself a finding about the gene and the disease.
episodic ataxia type 2 (continued). "The two patients with variants in CACNA1A showed decreased episodic ataxia events after acetazolamide treatment." (PMID 35719373, 2022). "Two patients with the CACNA1A mutations experienced recurrent cerebral infarction and episodic ataxia after febrile status epileptics, beginning in infancy or early childhood." (PMID 35719373, 2022). "Mutations in CACNA1A have been associated with several autosomal dominant neurologic disorders, including familial hemiplegic migraine type 1, episodic ataxia type 2 (EA2), and spinocerebellar ataxia type 6." (PMID 34395002, 2021). "CACNA1A pathogenic variants have been classically associated with several disorders, including episodic ataxia type 2, spinocerebellar ataxia type 6 and hemiplegic migraine (familiar and sporadic)." (PMID 33557884, 2021). "For example, nystagmus associated with episodic ataxia type 2 caused by CACNA1A pathogenic variant can be ameliorated with acetazolamide, and Leber congenital amaurosis caused by bi-allelic RPE65 variants can be treated with gene therapy." (PMID 35052368, 2021). "Shortly afterwards, mutations in the calcium channel gene CACNA1A were associated with episodic ataxia type 2 (EA2)." (PMID 33833732, 2021). "Mutations of CACNA1A were reported in familial hemiplegic migraine and episodic ataxia type-2, spinocerebellar ataxia type 6 (SCA6), and cognitive impairment, including intellectual disability, autism, epilepsy, and ADHD." (PMID 31963867, 2020). "Pt 4 presented with motor delay and episodic ataxia and was diagnosed with episodic ataxia type II (heterozygous CACNA1A mutation)." (PMID 33233562, 2020). "In the last two decades a large variety of loss of function mutations in CACNA1A, which encodes the voltage-gated calcium channel alpha1a subunit (Cav2.1), were found in patients with Episodic Ataxia type 2 (EA2)." (PMID 32466254, 2020). "CACNA1A mutations can cause episodic ataxia type 2 (EA2), epileptic seizures and familial hemiplegic migraine type 1 (FHM1)." (PMID 31364988, 2019). "Cav2.1 is mostly expressed in the cerebellum, consequently mutations in the Cacna1a gene are associated with several neurological disorders such as episodic ataxia and spino-cerebellar ataxia." (PMID 30319351, 2018). "Molecular genetic tests for episodic ataxia type 2 (EA2) usually target only the specific calcium channel gene (CACNA1A) that is known to cause EA2." (PMID 30314295, 2018). "The disease is genetically heterogeneous and is classified as episodic ataxia type 2 (EA2) when it is caused by a mutation in the CACNA1A gene, encoding the α1A subunit of the P/Q-type voltage-gated calcium channel Cav2.1." (PMID 28566750, 2017). "CACNA1A haploinsufficiency can cause episodic ataxia type 2 (MIM 108500), familial hemiplegic migraine type 1 (MIM 141500) and spinocerebellar ataxia 6 (MIM 183086)." (PMID 28713243, 2017). "Sanger-sequence analysis of the CACNA1A gene in a cohort of 49 Spanish individuals diagnosed with episodic ataxia allowed the identification of eight heterozygous variants in nine patients." (PMID 28566750, 2017). "In this study we aimed to perform an extensive mutation analysis of the CACNA1A gene in 49 unrelated patients with episodic ataxia by means of sequencing and CNV analyses to identify both disease-causing point variants and structural variants." (PMID 28566750, 2017). "In fact, mutations of the CACNA1A gene (which encodes a voltage-dependent calcium channel) were described both in episodic ataxia type 2 and in familial hemiplegic migraine, making plausible a genetic bridge between migraine and vestibular disorders." (PMID 28082766, 2016). "Aminopyridines have also been demonstrated to prevent ataxic episodes in patients with episodic ataxia type 2 (EA-2), a calcium channelopathy caused by a broad range of mutations of the CACNA1A gene of the P/Q calcium channel." (PMID 23451282, 2013).
episodic ataxia type 2 (continued). "Heterozygous variants in CACNA1A are associated with multiple neurodevelopmental phenotypes including developmental and epileptic encephalopathy (#617106), episodic ataxia type 2 (#108500) and migraine, familial hemiplegic with progressive cerebellar ataxia (#141500)." (PMID 40445116, 2025). "Episodic ataxia type 2 and spinocerebellar ataxia type 6: Other mutations in CACNA1A can cause episodic ataxia type 2 and spinocerebellar ataxia type 6, two ataxic disorders also associated with migraine as part of the clinical phenotype in many of those affected." (PMID 37628876, 2023). "In addition to SCA6, mutations in CACNA1A are associated with at least two dominantly inherited disorders, episodic ataxia type 2 and familial hemiplegic migraine, both of which clinically overlap with SCA6." (PMID 36187346, 2022). "For example, it may be effective in patients with episodic ataxia and migraine, where pathogenic variants in CACNA1A gene cause these conditions in the CACNA1A." (PMID 35673961, 2022). "Initially, mutations in the CACNA1A gene were identified in patients with familial hemiplegic migraine (FHM) (MIM#141500) or episodic ataxia type 2 (MIM#108500), in that phenotypes acetazolamide may prevent recurrence and improve symptoms." (PMID 34068417, 2021). "In addition, missense mutations in the CACNA1A gene are also associated with episodic ataxia type 2 and hemiplegic migraine." (PMID 33671313, 2021). "For example, a patient with a point mutation in CACNA1A might have a combination of different spells, including episodic ataxia, hemiplegic migraine, and/or seizures." (PMID 33833732, 2021). "The CACNA1A gene, another gene located at 19p12.13, encodes the alpha‐1A subunit of calcium voltage‐gated channels, and mutations in this gene have been reported with episodic ataxia type 2 and epilepsy." (PMID 32291963, 2020). "A case of episodic ataxia type 2 with a novel pathogenic variant in CACNA1A is described." (PMID 31640633, 2019). "Interestingly, some intragenic suppressor mutations resemble those found in CACNA1A in episodic ataxia type 2 (EA2) patients." (PMID 31364988, 2019). "Mutations in the CACNA1A gene, encoding for the P/Q-type voltage-gated calcium channel (Cav2.1), are known to result in neurological disorders, such as episodic ataxia type 2 (EA2), familial hemiplegic migraine type 1 (FHM1) and progressive spinal cerebellar ataxia type 6 (SCA6)." (PMID 30279196, 2018). "Episodic Ataxia type 2 (EA2) is the most frequent subtype of episodic ataxia caused by loss-of- function mutations in the CACNA1A gene encoding the alpha1A subunit of P/Q type voltage-gated Ca2+ channels (Cav2.1) mainly expressed in Purkinje and granule cells in the cerebellum." (PMID 27242528, 2016). "An example of this is the mutation of CACNA1A, which has a persistent impact on brain development and is involved in a spectrum of different clinical phenotypes, including episodic ataxia type 2, autosomal dominant spinocerebellar ataxia, hemiplegic migraine-1, and absence seizure." (PMID 24847307, 2014). "The allelic heterogeneity displayed by the CACNA1A gene also correlates with substantial clinical variation, as mutations in this gene are also responsible for two other autosomal dominant diseases: episodic ataxia type 2 (EA2, MIM #108500) and spinocerebellar ataxia type 6 (SCA6, MIM #183086)." (PMID 24498617, 2013). "However, CNV analysis has only reported this single deletion in CACNA1A so far in HM, and this type of alteration is more frequently found in episodic ataxia, where the typical pathogenic mechanism is a loss of function of the channel." (PMID 24498617, 2013). "In humans, mutations in CACNA1A are associated with channelopathies, such as spinocerebellar ataxia 6 and episodic ataxia type 2 as well as with more prevalent conditions such as familial hemiplegic migraine, dystonia, epilepsy, myasthenia and even intermittent coma." (PMID 18837980, 2008).
episodic ataxia type 2 (continued). "Therefore, mutations in the CACNA1A gene should be taken into account in the differential diagnosis of cerebellar atrophy in pediatric patients, irrespective of their history of familial hemiplegic migraine or episodic ataxia." (PMID 38785745, 2024). "Episodic ataxia type 2 (EA2), characterized by paroxysmal ataxia, dizziness and nausea, is associated with CACNA1A mutations responsible for loss of function and decreased Ca2+ influx." (PMID 36800925, 2023). "Mutations in human CACNA1A cause episodic ataxia type 2 (EA2) and familial hemiplegic migraine type 1 (FHM1), which have distinct clinical presentation from SCA6 and have been linked to altered calcium channel function, consistent with channelopathies." (PMID 32581696, 2020). "Thus, our finding could also suggest that seizures may be associated with different CACNA1A-related phenotypes including late-onset slowly progressive non-episodic ataxia." (PMID 32471306, 2020). "Variants in CACNA1A that encodes the pore-forming α1-subunit of human voltage-gated Cav2.1 (P/Q-type) Ca2+ channels cause several autosomal-dominant neurologic disorders, including familial hemiplegic migraine type 1, episodic ataxia type 2, and spinocerebellar ataxia type 6." (PMID 27005779, 2016). "Two CaV2.1 channelopathies—familial hemiplegic migraine type 1 (FHM1) and episodic ataxia type 2 (EA2)—result from mutations (gain- and loss-of-function, respectively) in human CACNA1A, which encodes the α1 subunit of presynaptic CaV2.1-type calcium channels." (PMID 24592212, 2014). "On the other hand, spinocerebellar ataxia type 6 (SCA6), which is caused by an abnormal expansion of CAG repeats in exon 47 of the CACNA1A gene, is characterized by slowly progressive cerebellar ataxia, but rarely presents with episodic ataxia-like symptoms." (PMID 40149486, 2025). "CACNA1A-related disorders include a spectrum of distinct clinical phenotypes such as episodic ataxia, familial hemiplegic migraine, and epilepsy, but also overlapping phenotypes with additional symptoms such as developmental delay and cognitive disability." (PMID 40703772, 2025). "Heterozygous variants in CACNA1A were historically associated with three well-defined neurological phenotypes: familial hemiplegic migraine type 1 (FHM1), episodic ataxia type 2 (EA2), and spinocerebellar ataxia type 6 (SCA6)." (PMID 39110218, 2024). "Earlier CACNA1A cohorts included specifically patients with episodic ataxia or hemiplegic migraine phenotype." (PMID 39110218, 2024). "Episodic ataxia type 2 (EA2), developmental and epileptic encephalopathy 42 (DEE42), and familial hemiplegic migraine are also due to CACNA1A variants." (PMID 38003592, 2023). "Clinical similarity between vestibular migraine and episodic type 2 ataxia, suggests shared pathophysiological mechanisms, such as voltage-gated calcium channel (CACNA1A) changes, also found in familial hemiplegic migraine." (PMID 35976301, 2022). "For example, in episodic ataxia type-2 (EA-2), an autosomal dominant disorder, mutations in the gene CACNA1A that encodes CaV2.1 predict truncated forms of this channel." (PMID 33664982, 2021). "Accordingly, pathogenic CACNA1A variants have been initially identified in the setting of familial hemiplegic migraine type 1 (FHM1) and episodic ataxia type 2 (EA2)." (PMID 33544220, 2021). "Mutations in CACNA1A have been associated with several autosomal dominant neurologic disorders, including familial hemiplegic migraine type 1 (FHM1), episodic ataxia type 2 (EA2), and spinocerebellar ataxia type 6 (SCA6)." (PMID 34395002, 2021). "CACNA1A testing belongs to the standard assessment of hemiplegic migraine or episodic ataxia, especially in the setting of a positive family history or when chronic cerebellar signs are present." (PMID 33737904, 2021). "CACNA1A variants underlie three neurological disorders: familial hemiplegic migraine type 1 (FHM1), episodic ataxia type 2 (EA2) and spinocerebellar ataxia type 6 (SCA6)." (PMID 33544220, 2021).
episodic ataxia type 2 (continued). "Mutations in the CACNA1A gene were identified as responsible for at least three autosomal dominant disorders: FHM1 (Familial Hemiplegic Migraine), EA2 (Episodic Ataxia type 2), and SCA6 (Spinocerebellar Ataxia type 6)." (PMID 32336275, 2020). "For example, two well-studied channelopathies—episodic ataxia type 2 (EA2) and familial hemiplegic migraine type 1 (FHM1)—arise from point mutations in the CACNA1A gene that encodes the α1A subunit." (PMID 32116539, 2019). "In addition to FHM1, heterozygous mutations within CACNA1A can cause two other neurological disorders, episodic ataxia type 2 (EA2; MIM #108500) and spinocerebellar ataxia type 6 (SCA6; #MIM 183086)." (PMID 31226929, 2019). "The independent occurrence of epilepsy and other paroxysmal disorders in a single gene was also reported for CACNA1A, an epileptic encephalopathy that has been recognized as a separate phenotype in addition to episodic ataxia and familial hemiplegic migraine." (PMID 31572294, 2019). "Mutations in the pore-forming unit of the P/Q-type VGCC (CACNA1A) in humans give rise to the channelopathies familial hemiplegic migraine type 1 (FHM1) and episodic ataxia type 2 (EA2)." (PMID 29020622, 2017). "Here we report an exhaustive screening of the CACNA1A gene in a large sample of patients with episodic ataxia, which was addressed through Sanger sequencing and CNV analyses." (PMID 28566750, 2017). "We performed a mutational screening of the CACNA1A gene, including the promoter and 3′UTR regions, in 49 unrelated patients diagnosed with episodic ataxia." (PMID 28566750, 2017). "Episodic ataxia type 2 is caused by mutations in CACNA1A, which encodes the pore-formingsubunit of the voltage-gated calcium channel Cav2.1." (PMID 26912519, 2016). "Different mutations of the CACNA1A genes, which encode the immunogenic alpha-1A VGCC subunit (Cav2.1), can produce the autosomal dominant SCA type 6, episodic ataxia type 2 (EA2) or familial hemiplegic migraine 1 (FHM1)." (PMID 26377184, 2015). "Genetic loci and clinical features of familial episodic ataxias have been defined in linkage disequilibrium studies with mutations in neuronal genes KCNA1 and CACNA1A." (PMID 22379397, 2011). "This entity overlaps the phenotype of the CACNA1A disorder known as “episodic ataxia type 2”." (PMID 41240219, 2025). "Mutations in CACNA1A are associated with SCA6 and episodic ataxia type 2 (EA2)." (PMID 37374132, 2023). "CAG repeats in the last exon of the longest isoform of CACNA1A cause SCA6, and missense mutations affecting the calcium channel-encoding sequence cause progressive cerebellar ataxia, familial hemiplegic migraine (FHM1), and episodic ataxia type 2 (EA2)." (PMID 35326432, 2022). "Non-CAG missense mutations found in the CACNA1A gene give rise to two other distinct diseases—episodic ataxia type 2 and familial hemiplegic migraine-1." (PMID 34829728, 2021). "Cumulatively, our findings show that in patients with episodic ataxia and hemiplegic migraine EEG slowing between the attacks and intermittent IEDs during childhood and adolescence are indicative—together with a positive family history—of a CACNA1A mutation." (PMID 33544220, 2021). "We retrieved from our database 18 patients with episodic ataxia or sporadic hemiplegic migraine which had been tested negative for CACNA1A variants." (PMID 33544220, 2021). "Episodic ataxia (EA) is associated with SCA, and mutations in calcium channel genes may lead to EA; for example, mutations in CACNA1A and CACNB4 lead to EA2 (MIM: 108500) and EA5 (MIM: 613855), respectively." (PMID 31291898, 2019). "Here we present a case of a proband with a complex episodic ataxias (EA)/seizure phenotype with an EA-affected father; and an unaffected mother, all negative for CACNA1A gene mutations." (PMID 30314295, 2018). "Moreover, in patients with migraine phenotypes and episodic ataxia is becoming mandatory the screening of gross rearrangements of CACNA1A gene for a complete genetic workup." (PMID 30167989, 2018).
episodic ataxia type 2 (continued). "All types may occur with vertigo or associated with episodic ataxia, especially FHM type I (associated with CACNA1A gene)." (PMID 28082766, 2016). "Familiar episodic ataxias are rare cause of recurrent vertigo, but molecular genetics has identified several mutations on KCNA1 and CACNA1A genes that suggest a key role for voltage-gated channels and solute carriers in the plasma membrane of neurons in recurrent vertigo." (PMID 22379397, 2011). "Episodic Ataxia Type 2 (EA2) is related to genetic changes in CACNA1A gene among others, such as ATP1A2 gene." (PMID 40111503, 2025). "Moreover, given the encouraging outcome reported by Martakis and colleagues that N-acetyl-leucine acts as a new potential treatment for CACNA1A-related disorders, we predict that this compound could be beneficial for CACNA1A-related episodic ataxia." (PMID 40111503, 2025). "Moreover, gender differences were described in various CACNA1A gene mutations, e.g., SCA 6 as an example of trinucleotides extension, episodic ataxia type 2 (EA2) in case of loss-of-function, and familial hemiplegic migraine-1 (FHM1) an example of gain-of-function missense mutation." (PMID 32733356, 2020). "Taking into account the large phenotypic heterogeneity, our data further support the view that testing for non-CAG trinucleotide repeat CACNA1A mutations should also be performed in patients with non-episodic ataxia of unknown cause." (PMID 32471306, 2020). "Multiple CNVs affecting SPG7 (n = 4), CACNA1A (n = 3), SGCE (n = 3), NKX2-1 (n = 2) and SPAST (n = 2) were detected in individuals with episodic ataxia, dystonia, or spastic paraplegia, respectively." (PMID 36781956, 2023). "The presence of a mutation in the CACNA1A gene, which encodes the α1A-subunit of voltage-gated P/Q-type calcium channels (Cav2.1), results in an array of neurological disorders including SCA6, episodic ataxia type 2 and familial hemiplegic migraine type 1." (PMID 32765211, 2020). "Due to these nonepileptic events, molecular testing for episodic ataxia panel (CACNA1A, CACNB4, KCNA1, PNKD, PRRT2, SLAC1A3, VAMP1) was requested, and this came back normal." (PMID 37469362, 2023). "Non-polyglutamine CACNA1A variants underlie familial hemiplegic ataxia type 1 (FHM1) and episodic ataxia type 2 (EA2)." (PMID 33737904, 2021). "Episodic ataxia type 2 (EA2), whose clinical features include the lack of voluntary coordination of muscle movements and epileptic seizures, is associated with a range of missense, nonsense-, and splice site mutations throughout the CACNA1A gene." (PMID 31364988, 2019). "Mutations in CACNA1A are associated with a few neurological diseases, including FHM, episodic ataxia type 2 (EA2), spinocerebellar ataxia type 6 (SCA6) and nonprogressive congenital ataxia (NPCA), and epilepsy." (PMID 33799975, 2021). "In non-expansion CACNA1A disorders, seizures and epileptiform activity in EEG are typically observed in childhood, before onset of hemiplegic migraine/episodic ataxia and abate later in life." (PMID 41240219, 2025).